MIR1-1 (microRNA 1-1)
Synonyms: hsa-mir-1-1; MIRN1-1; miRNA1-1; mir-1-1
Gene: MicroRNA gene on chromosome 20 (62,554,306 to 62,554,376, forward strand). Ensembl gene ENSG00000199017.
Gene Ontology:
Biological process: miRNA-mediated post-transcriptional gene silencing
Cellular component: RISC complex
Homologues: Orthologues: chimpanzee ptr-mir-1-1 (100% identical), macaque mml-mir-1-1 (100% identical), rat Mir1b (97% identical), guinea pig MIR1-1 (96% identical), mouse Mir1a-1 (96% identical), pig ssc-mir-1 (94% identical), tropical clawed frog xtr-mir-1a-2 (87% identical), zebrafish mir1-1 (87% identical), dog MIR1-1 (83% identical), Caenorhabditis elegans cel-mir-1 (69% identical), Drosophila melanogaster mir-1 (63% identical). Paralogues in human: MIR1-2 (79% identical), MIR206 (75% identical).
Diseases named in the same sentence as MIR1-1 in open-access papers:
MIR1-1 is named in the same sentence as 5 diseases in open-access papers, as found by Europe PMC text mining. Sharing a sentence is not in itself a finding about the gene and the disease. The quoted sentences say what the papers report.
atrial fibrillation (1 paper, 2013). A disorder characterized by an electrocardiographic finding of a supraventricular arrhythmia characterized by the replacement of consistent P waves by rapid oscillations or fibrillatory waves that vary in size, shape and timing and are accompanied by an irregular ventricular response. "We re-sequenced the MIR1-1, MIR1-2, MIR133A1, MIR133A2, and MIR133B genes, that encode the cardiac-enriched miRNAs, miR-1 and miR-133, in 120 individuals with familial atrial fibrillation and identified 10 variants, including a novel 79T > C MIR133A2 substitution." (PMID 23497314, 2013).
breast carcinoma (1 paper, 2024). "Furthermore, a wide range of miRNAs has been related to breast cancer, either acting as tumor suppressors (e.g., MIR100, MIR1-1, or MIR114) or oncogenes (e.g., MIR115, MIR17, or MIR224)." (PMID 39125744, 2024).
type 2 diabetes (1 paper, 2024). "The value of MIR1-1 gene expression was statistically significantly higher in patients with type 2 diabetes (median: 0.352; mean: 0.386; standard deviation: 0.923) compared to patients without type 2 diabetes (median: 0.147; mean: −0.02; standard deviation: 0.824)." (PMID 38256676, 2024).
cancer (1 paper, 2015). A tumor composed of atypical neoplastic, often pleomorphic cells that invade other tissues. "The differentially regulated miRNAs include Mir1-1, Mir125b-2 and Mir141, which have well-known roles in cancer development." (PMID 26461935, 2015).
MIR1-1 also shares sentences with these, for which no sentence is quoted: tumor (1 paper).